PODXL (podocalyxin like)
Diseases named in the same sentence as PODXL in open-access papers (continued):
Sharing a sentence is not in itself a finding about the gene and the disease.
cancer (continued). "Since the core protein of PODXL is aberrantly expressed by many human tumors and its expression is consistently linked to poor prognosis, this PODO447 epitope serves as an excellent candidate for the development of targeted cancer immunotherapies." (PMID 38188285, 2023). "The authors show that miR-5100 decreases the aggressiveness of the pancreatic cancer tumor models through the inhibition of PODXL, which promotes anti-adhesive and migratory characteristics of various cancers, and high levels of PODXL correlates with poor prognosis in many of them." (PMID 36551682, 2022). "PODXL as a mediator for metastasis may provide a useful biomarker for assessing metastasis potential and prognosis in cancer patients." (PMID 34201212, 2021). "PODXL is reported to mediate cancer cell migration and invasion." (PMID 34201212, 2021). "Taken together, among the SALL2 target genes functionally related in GBM, PODXL might also have a functional relationship with SALL2 in other cancer types." (PMID 33692826, 2021). "PODXL promotes cancer development and aggressiveness by activating MAPK and PIK3 pathways." (PMID 34422820, 2021). "PODXL plays an important role in both normal tissue development and cancer progression." (PMID 34201212, 2021). "Furthermore, many cancers, especially those that originated from the epithelium, have been reported to overexpress PODXL." (PMID 34201212, 2021). "PODXL was expected to be a novel therapeutic and monitoring biomarker in certain cancers, because the high expressed PODXL might be a potential indicator of poor prognosis of cancers." (PMID 32615943, 2020). "PODXL expression was correlated with poor survival of cancer patients." (PMID 32669966, 2020). "Recent researches indicated that the expression level and location of PODXL could be a new biomarker to assess the prognosis of various types of cancers." (PMID 32615943, 2020). "Several studies provide evidence of a role for PODXL in cancer metastasis in vitro and in vivo." (PMID 32046309, 2020). "Therefore, we proceeded a meta-analysis on PODXL in various human cancers to find its prognostic value and followed confirmation using the TCGA datasets." (PMID 32615943, 2020). "First, PODXL was reported to be overexpressed in various cancers." (PMID 29748877, 2019). "Recent studies have suggested that the role of PODXL may be of pivotal importance in the development and progression of various cancers." (PMID 29748877, 2019). "Furthermore, we need to combine anti-PODXL antibodies with anti-cancer drugs or include them in novel antitumor regimens, including T cells and viruses, to exert antitumor activity against cancer cells." (PMID 29854293, 2018). "Currently, the effect of PODXL on cancer progression remains largely unknown; our finding therefore not only favors clinical detection of PODXL but also advances the understanding of PODXL effect on regulating cancer microenvironment." (PMID 30277651, 2018). "•PODXL is involved in cancer growth, invasion, and metastasis." (PMID 29872738, 2018). "This group recently expanded their research to other cancers within the upper gastrointestinal tract, and successfully demonstrated that reciprocal changes in ADAR1 and ADAR2 coordinated cancer pathogenesis via hypo-editing of the podocalyxin-like protein 1 gene (PODXL)." (PMID 30563560, 2018). "In addition, we first found that LEA/PODXL can be secreted in exosomes from cancer cells and CRC patient peripheral blood." (PMID 30277651, 2018). "In many reports, it is the presence (not the absence) of PODXL and other sialomucins has been linked to cancer progression." (PMID 30498210, 2018). "Furthermore, we investigated the effect of PODXL on the growth of 3D cells with cancer stem cell-like properties." (PMID 29854293, 2018). "Nevertheless, the prognostic role of PODXL expression in cancers was controversial." (PMID 28881743, 2017).
cancer (continued). "In terms of ethnicity, the results demonstrated that high PODXL expression was an unfavorable prognostic factor in cancers in European (HR=1.67, 95%CI=1.40-1.99, p<0.00001; I2=48%, p=0.05), in North American (HR=1.92, 95%CI=1.48-2.49, p<0.00001) and in Asian (HR=1.51, 95%CI=1.12-5.62, p=0.03)." (PMID 28881743, 2017). "Therefore, to further explore the relationship between the PODXL expression and prognosis of cancers in Asian and North American, more relevant studies should be put into effect in Asian and North American." (PMID 28881743, 2017). "This study aims to summarize the prognostic significance of PODXL expression in cancers." (PMID 28881743, 2017). "The functional role of PODXL in tumorigenesis is largely unknown, but it has been demonstrated to promote cancer cell invasion and migration and to enhance metastatic potential." (PMID 27478410, 2016). "The role of PODXL in cancer is unknown but it can be speculated that also PODXL may have a role in EMT." (PMID 26674770, 2015). "It has been shown that, in cancer, poor prognosis associates with distinct membranous PODXL expression, rather than cytoplasmic expression." (PMID 26053486, 2015). "Positive PODXL expression both by the polyclonal antibody HPA2110 and the monoclonal antibody HES9 was associated with high SPF by flow cytometry and Ki-67 staining, both being markers of high proliferation of cancer cells and thus of worse prognosis." (PMID 26674770, 2015). "A previous study has suggested that PODXL, a transmembrane protein that has been found critical for malignant progression in a variety of cancers, may also contribute to cancer chemoresistance." (PMID 25915207, 2015). "Recent studies have shown that PODXL is also expressed in a variety of cancers." (PMID 25915207, 2015). "PODXL reportedly is an essential driver of malignant progression in many cancers." (PMID 25915207, 2015). "Membranous PODXL expression was denoted in 11/63 (17.5 %) primary and 2/24 (8.3 %) metastatic I-type carcinomas, and in 53/107 (49.5 %) primary and 23/63 (36.5 %) metastatic PB-type carcinomas." (PMID 26028992, 2015). "One proposal is that distinct membranous PODXL expression, but not cytoplasmic expression, associates with poor prognosis in different cancers." (PMID 25004863, 2014). "The difference in staining pattern may reflect different PODXL function in cancer compared to normal tissue." (PMID 25004863, 2014). "PODXL has also been shown to be expressed in several cancers with stem-like cell populations." (PMID 24146797, 2013). "The role of PODXL in cancer was first described in testicular cancer." (PMID 23819542, 2013). "Moreover, given the heterogeneous nature of HGSC, there may be other factors/mechanisms that may interact with PODXL to support proliferation and survival of cancer spheroids." (PMID 38553472, 2024). "However, it is unclear whether TGFβ and PODXL interactions are involved in cancer-progression resistance after radiation exposure in CRC." (PMID 34440856, 2021). "Moreover, understanding the involvement of PODXL in cancer progression may offer further insight into the mechanisms underlying the metastasis process for developing better treatment." (PMID 34201212, 2021). "While the detailed molecular mechanisms by which PODXL promotes tumourigenesis remain to be elucidated, PODXL is proposed to interact with several proteins and downstream signalling pathways that are critical in promoting cancer metastasis and subsequent invasion." (PMID 34201212, 2021). "Thus, PODXL may be a potential biomarker for predicting patient outcomes and identifying subgroups with higher risks of developing aggressive cancer phenotypes." (PMID 34201212, 2021). "Therefore, PODXL may act as an immunomodulatory molecule in cancer cells to suppress NK cell detection and evade immunosurveillance." (PMID 34201212, 2021). "Furthermore, available articles manifested that PODXL may be an independent prognostic marker in cancers." (PMID 29748877, 2019).
cancer (continued). "Therefore, more and more researchers focused on the role of PODXL in cancers." (PMID 28881743, 2017). "Besides, the antibody type influenced the prognostic role of PODXL expression in various cancers." (PMID 28881743, 2017). "Therefore, the PODXL/Bmi1 signaling axis identified in this study may also play important roles in the chemoresistance and progression of other cancers besides OTSCC, which needs to be verified in future studies." (PMID 25915207, 2015). "Another important goal is the targeting of cancer-specific antigens using a cancer-specific mAb (CasMab) because EGFR, HER2, PODXL, and CD44 are widely expressed in normal tissues." (PMID 33000243, 2020). "PODXL has been reported to upregulate and form a complex with the glucose-transporter 3 (GLUT3) in embryonal carcinoma cancer stem cells." (PMID 32046309, 2020). "We found a correlation between PODXL and EGFR in these cancers, and a synergistic adverse effect on survival." (PMID 32587323, 2020). "Emerging evidence suggested that PODXL was involved in the process of invasion, metastasis and EMT in various cancers." (PMID 29748877, 2019). "In accordance with our recent study, DIO1 expression resulted also in suppression of TGFBI, and several other proteins (e.g. PODXL, CD74) that promote RCC progression or act as oncogenic proteins in other cancers (e.g. FMNL2, APBB1IP, ASAP1, and LRRFIP1)." (PMID 29272308, 2017). "Using tissue microarrays and immunohistochemistry, PODXL and RBM3 expression was evaluated in 272 incident UBC cases from the prospective, population-based cohort study Malmö Diet and Cancer." (PMID 28293425, 2017). "In conclusion, it was revealed that high PODXL expression is an unfavorable predictor of OS, DSS and DFS in various cancers, and high PODXL expression is a promising prognostic biomarker for cancers, especially for patients in European." (PMID 28881743, 2017). "Further studies should aid in understanding the function of PODXL in CRC and the reasons for differences in expression between cancers of the RHC and the LHC." (PMID 25004863, 2014). "Here, cancers of the RHC were more poorly differentiated, had higher PODXL expression, and were in older patients, more often female, although differences in age and gender were not statistically significant." (PMID 25004863, 2014). "Analysis of the differences between cancers of the RHC and LHC showed cancers of the RHC to exhibit higher expression of PODXL (p < 0.001) and be more poorly differentiated (p < 0.0001)." (PMID 25004863, 2014). "Thus, PODXL may play a critical role in cancer development and aggressiveness." (PMID 23596468, 2013). "In this study, we examined the presentation of PODXL in HGSC patient tissues and cell lines, and investigated its potential role in promoting cancer spheroid characteristics that may confer survival advantage." (PMID 38553472, 2024). "However, it would be worthwhile to investigate the cancer specificity of the PcMab-6 single-chain variable fragment and the efficacy of CAR-T therapy against PODXL-positive tumors." (PMID 38203331, 2023). "In addition, PODXL has been shown to act as an EMT mediator, to be involved in metastatic behavior, and to induce actin recruitment in several types of cancer cells." (PMID 34440856, 2021). "Of note, these cancers are not of epithelial origin, and further studies are required to elucidate the role of PODXL in chemoresistance in epithelial cancers." (PMID 34201212, 2021). "The interactions between PODXL, ezrin, and NHERF-1/2 have been reported to activate downstream intracellular signalling via the RhoA, Rac1, Cdc42, MAPK, and PI3K pathways to promote cancer metastasis." (PMID 34201212, 2021). "Furthermore, ND‐1 showed superior sensitivity and specificity to commercial mAb 3D3, which recognizes PODXL core protein, in CRC samples, and LEA/PODXL can be secreted in exosomes derived from cancer cells and CRC patient plasma." (PMID 30277651, 2018).
cancer (continued). "Patients with high PODXL expression in their pre-neoadjuvant biopsies had a superior histopathologic response (notably 36% with no residual cancer cells) compared to those with negative (p = 0.010) or low (p = 0.013) PODXL expression." (PMID 30355278, 2018). "Patients with high PODXL expression in their pre-neoadjuvant biopsies had a superior histopathologic response (notably 36% with no residual cancer cells) compared to those with negative or low PODXL expression, and were all recurrence-free at last follow-up." (PMID 30355278, 2018). "Using the cell line expressing the highest levels of PODXL as a model and CRISPR/Cas9 gene editing, we further illustrated that PODXL promoted cell proliferation within the spheroid, and fostered the formation of dense cancer spheroids which were resilient to fragmentation." (PMID 38553472, 2024). "Taking advantage of this peculiarity of neoplastic cells, we recently developed a novel monoclonal antibody (mAb), named PODO447, that targets a glycopeptide epitope of PODXL expressed on cancer cells, but is absent on normal, PODXL-expressing podocytes and vascular endothelia." (PMID 38188285, 2023). "Accordingly, inhibiting EGFR may affect EMT and inhibit cancer cell migration, although the association between EGFR and EMT is not as apparent as it is for PODXL." (PMID 32587323, 2020). "Thus, PODXL and NRARP may be conserved SALL2 targets across species, tissues, and cancer types." (PMID 33692826, 2021). "E- and L-selectin were reported as functional ligands in cancer cells, but we are not sure whether L- or E-selectin can promote SSC proliferation through PODXL." (PMID 34422820, 2021).
kidney disease (6 papers, 2019 to 2025). "Clinically, patients harboring monoallelic truncating mutations in the PODXL gene displayed the onset of renal disease during their third decade of life and experienced alterations on urinalysis, such as proteinuria and/or elevated serum creatinine and albumin levels." (PMID 40282423, 2025). "Dominant and recessive mutations in podocalyxin (PODXL) are associated with human kidney disease." (PMID 32523052, 2020). "With respect to a wider role for podocalyxin in kidney disease, it is noteworthy that soluble urinary PODXL has been consistently documented in patients with podocytopathies in a wide range of renal disorders." (PMID 32523052, 2020). "Besides the renal disorders, our investigation further proposed down-regulated expressions of WT1 and PODXL as desirable indicators for incremental risk and unfavorable prognosis (i.e., renal survival) of IMN." (PMID 31352863, 2019).
infection (4 papers, 2020 to 2022). The state of being infected such as from the introduction of a foreign agent such as serum, vaccine, antigenic substance or organism. "No significant changes in the levels of expression of podocyte marker genes (WT1, PODXL, NPHS1, NPHS2, and MAFB) or for tubular marker genes (SLC3A1 and SLC16A1) were found after infection comparing WT and ACE2 KO kidney organoids." (PMID 35561674, 2022). "Using semiautomated image analysis quantification, we found that 12.4% of the total organoid area and 24.5% of the total LTL+ area were infected, respectively, whereas infection of podocytes (PODXL+) was not significant." (PMID 34767537, 2021).
adenocarcinoma (3 papers, 2015 to 2018). A common cancer characterized by the presence of malignant glandular cells. "It has been shown that PDAC cells are generally positive for PODXL, but other adenocarcinomas of the biliary and gastrointestinal tract are mainly negative." (PMID 26053486, 2015). "It would also be of interest to assess whether there is a relationship between PODXL expression and the molecular subtypes proposed by The Cancer Genome Atlas for gastric and esophageal adenocarcinoma." (PMID 30355278, 2018).
breast (2 papers, 2018 to 2020). "Moreover, upregulated PODXL might be crucial in the initiation of colorectal carcinogenesis by the disruption of the multigene network system regulating cell adhesion and the cytoskeleton." (PMID 33537062, 2020).
genetic disorder (1 paper, 2025). "NMD plays a very important role not only in understanding the biological cause of variant pathogenicity in genetic disease, but also helping to address gene therapies by increasing the production of full-length PODXL protein." (PMID 40282423, 2025).
immune system diseases (1 paper, 2015). "Specifically, eight genes (IRF5, UBA7, TMTC1, GSTM3, FBN2, OAS1, PODXL, ITGA2) were previously associated with immune system diseases in at least one study." (PMID 25874939, 2015).
neurodegenerative disease (1 paper, 2025). A disorder of the central nervous system characterized by gradual and progressive loss of neural tissue and neurologic function. "As BBB breakdown is thought to contribute to neurodegenerative diseases such as AD, PODXL may play a crucial role in AD pathogenesis, potentially through its impact on BBB integrity and neuroinflammation." (PMID 40491569, 2025).
PODXL also shares sentences with these, for which no sentence is quoted: renal cell carcinoma (5 papers); esophageal cancer (4); leukemia (3); anaplastic astrocytoma (1); astrocytic tumor (1); atopic dermatitis (1); autism (1); B-cell acute lymphoblastic leukemia (1); Barrett esophagus (1); bladder (1); brain tumors (1); cardiac failure (1); cholangiocarcinoma (1); chronic myeloid leukemia (1); ciliopathies (1); Cognitive impairment (1); colorectal tumours (1); diabetes (1); Dyskinesia (1); Dystonia (1); embryonal carcinoma of the testis (1); endometrial adenocarcinoma (1); hematologic malignancies (1); hematological cancers (1); IgA nephropathy (1); infectious disease (1); influenza infection (1); invasive breast carcinoma (1); kidney cancer (1); lymphoma (1).
A further 19 diseases each share a sentence with PODXL in 1 paper.